TIA1 (TIA1 cytotoxic granule associated RNA binding protein)
Diseases named in the same sentence as TIA1 in open-access papers (continued):
Sharing a sentence is not in itself a finding about the gene and the disease.
tauopathy (continued). "This phenotype is observed predominantly in female mice, and TIA1 haploinsufficiency exacerbates neuroinflammation in tauopathy." (PMID 34884582, 2021). "Here we demonstrate that, as in the peripheral immune system, TIA1 plays an important role in the neuroimmune response to chronic stress in the form of tauopathy." (PMID 32327969, 2020). "Overall, these results are consistent with the idea that at normal levels TIA1 decreases phagocytosis and processing of antigen, resulting in reduced adaptive immune functions in tauopathy." (PMID 32327969, 2020). "In this system, TIA1 knockdown prevented tau misfolding and toxicity, and highlighted a role for RNA-binding proteins as therapeutic targets in tauopathies." (PMID 33255694, 2020). "In support of this idea, TIA1-mediated stress granule formation in microglia significantly reduces their phagocytic capabilities; thus, reduction of TIA1 would be expected to enhance protective microglial phagocytic activity in tauopathy." (PMID 32327969, 2020). "To further characterize the relationship between TIA1 reduction, inflammation, and tauopathy, we have begun generating a conditional knock-out mouse model, in which TIA1 is specifically removed in either microglia or neurons in P301S mice." (PMID 32327969, 2020). "The putative role of TIA1 as a regulator of the peripheral immune response led us to investigate the effects of TIA1 on neuroinflammation in the context of tauopathy, a chronic stressor in the neural environment." (PMID 32327969, 2020). "Overall, the patterns of dysfunctional RNA splicing in AD brain and tauopathy models are largely overlapping and many are predicted to be regulated by TIA1." (PMID 33255694, 2020). "Our data show that both TIA1 haploinsufficiency and TIA1 knockout exacerbate neuroinflammatory processes in advanced stages of tauopathy, suggesting that TIA1 dampens the immune response in the central nervous system during chronic stress." (PMID 32327969, 2020). "The current study uses tau seeding and propagation models to investigate the mechanisms through which TIA1 impacts on tauopathy." (PMID 30465259, 2019). "Many of the RBPs associated with the spliceosome aggregate in AD and mouse models of tauopathy, some co-localizing with tau inclusions, such as TIA1, and others forming independent inclusions, such as TDP-43, U1–70K, and G3BP1." (PMID 31875547, 2019). "The critical role of TIA1 enabled further investigation into the pathophysiological mechanisms through which TIA1 contributes to tauopathy." (PMID 30465259, 2019). "The relevance of the SG pathway to tauopathy was recently demonstrated by our observation that TIA1 reduction protects against disease progression in a mouse model of tauopathy." (PMID 30068389, 2018). "Co-accumulation of tau oligomers with TIA-1 and other RBPs has been demonstrated in a tauopathy animal model and it has been shown that reduction of TIA-1 levels led to reduced tau oligomers formation, rescuing behavioral deficits in these animals." (PMID 30367664, 2018). "Recent studies from our laboratory also implicate RBPs such as TIA1 in the pathophysiology of AD and other tauopathies." (PMID 28420962, 2017). "The authors also showed that the proteins found in the interacting proteome of TIA1 colocalised with phosphorylated tau in brain tissues of tauopathy mice models." (PMID 28937634, 2017). "Additionally, LLPS of wild-type TIA1 has been found to promote the phase separation and toxic oligomerisation of tau, exacerbating tauopathies." (PMID 41188647, 2025). "Besides, LLPS-mediated aggregation of TIA1 also controls tauopathy, thus promoting the degeneration of axons." (PMID 41188647, 2025). "TIA1 also plays an important role in both peripheral inflammation and in tauopathy, but the involvement of TIA1 in CNS neuroinflammation is poorly understood." (PMID 32327969, 2020).
tauopathy (continued). "The requirement for TIA1 in the pathophysiology of tauopathy was demonstrated by recent findings that TIA1 reduction prolongs lifespan and provides neuroprotection in the PS19 P301S tau mouse model, in a manner that reduced oligomeric tau but increased fibrillary tau." (PMID 30465259, 2019). "The mechanism through which TIA1 reduction protects against tauopathy, and whether TIA1 modulates the propagation of tau, are unknown." (PMID 30465259, 2019). "While the relative contributions of direct TIA1 function, differential RBP expression, and altered proteostasis or SG dynamics remain to be determined, the ability of TIA1 reduction to rescue the splicing dysfunction demonstrates the importance of RBP biology in the pathophysiology of tauopathies." (PMID 31875547, 2019). "Our transcriptomic analyses indicate that the behavioral protection from tauopathy in P301S Tia1+/− mice is associated with a reversion to normal splicing of synaptic mRNAs." (PMID 31875547, 2019). "Recent studies show that RBPs, such as TIA1, also contribute to the pathophysiology of tauopathy." (PMID 30465259, 2019). "While this result does not demonstrate a direct role for TIA1 in mediating alternative splicing of Gria2, Snap25, or Camk2b, the results indicate that normalization of splicing represents a clear component of the neuroprotection provided by TIA1 reduction in tauopathy." (PMID 31875547, 2019). "Rescuing SNHG8 expression leads to reduced stress granule formation and reduced TIA1 levels in immortalized cells and in MAPT mutant neurons, suggesting that dysregulation of this non-coding RNA is a causal factor driving stress granule formation via TIA1 in tauopathies." (PMID 37730840, 2023). "The neuroinflammatory response was significantly higher in the hippocampus of both P301S TIA1+/– and P301S TIA1–/– mice compared to P301S TIA1+/+ mice in late-stage of disease, consistent with the idea that TIA1 dampens the neuroinflammatory response during the chronic stress of tauopathy." (PMID 32327969, 2020). "While reduction of TIA1 may lead to harmful cytotoxic inflammation and oxidative stress, it also restores microglial phagocytic function, which may prove to be beneficial in the context of tauopathy." (PMID 32327969, 2020). "We have recently demonstrated that haploinsufficiency of the RNA binding protein (RBP) T-Cell Intracellular Antigen 1 (TIA1) significantly reduces neurodegeneration in the P301S mouse model of tauopathy, however the underlying mechanism(s) of action are not known." (PMID 32327969, 2020). "Thus, the upregulation of UBE2I in the PS19 mouse might be a compensatory response to the neurodegenerative changes or a tauopathy-independent effect of Tia1 heterozygosity." (PMID 31875547, 2019). "However, depletion or deletion of TIA1 in these models also intensifies neuroinflammatory processes in advanced stages of the disease, suggesting that TIA1 acts as a translational repressor that mitigates inflammation in the central nervous system during chronic stress produced by tauopathy." (PMID 35163320, 2022). "The disease modifying effects of TIA1 reduction, the colocalization of TIA1 with somatodendritic tau, and the effects of somatodendritic tau on SG accumulation raise the possibility that dysfunction of RNA metabolism might be an important contributor to the pathophysiology of tauopathy." (PMID 31875547, 2019). "Using the Abcam antibody, we consistently observed TIA1 colocalization with CP13 positive phospho-tau in the rTg4510 and the PS19 mouse models of tauopathy." (PMID 30068389, 2018). "Our results are in agreement with the study by Leyns and coworkers, which suggested that increased TREM2 expression may exacerbate tauopathy, as we observed increased levels of AT8 + phospho-tau in the dentate gyrus of TIA1 knockout P301S animals." (PMID 32327969, 2020).
tauopathy (continued). "In order to determine how the RNA transcriptome is altered in PS19 tauopathy mice, we isolated total RNA extracts from the cortex of 9-month-old wild-type (WT), PS19 (P301S Tia1+/+) and P301S Tia1+/− mice (refer to the STAR Methods for a detailed description of the breeding scheme)." (PMID 31875547, 2019). "We proceeded to show that TIA1 reduction (haploinsufficiency) is also protective in vivo, reducing neurodegeneration, rescuing cognition and increasing survival in the PS19 mouse model of tauopathy." (PMID 30068389, 2018). "Plasma TIA-1 concentrations were measured in Alzheimer’s disease, mild cognitive impairment due to AD (MCI-AD), vascular cognitive impairment (VCI), and other neurodegenerative diseases (NDs: synucleinopathies and tauopathies), and compared to healthy controls." (PMID 41877170, 2026). "We documented propagation of S1p-induced tauopathy (CP13 staining) in these cultures and then used immunoblotting to quantify seeded tau using the pTau antibody CP13; these studies demonstrated that TIA1 knock down reduced levels of pTau induced by S1p seeding." (PMID 30465259, 2019). "Importantly, TIA1 reduction in wildtype mice did not result in increased levels of proinflammatory cytokine expression, indicating that a chronic stressor (e.g., tauopathy) must be present to trigger significant pro-inflammatory cytokine release (data not shown)." (PMID 32327969, 2020). "RESULTS: Plasma TIA-1 levels were significantly reduced in AD, MCI-AD, VCI, and non-AD neurodegenerative diseases (synucleinopathies and tauopathies) compared to healthy controls, with the greatest reductions observed in non-AD neurodegenerative diseases." (PMID 41877170, 2026).
Welander distal myopathy (18 papers, 2014 to 2026). "Splicing of survival of motor neurone 2 (SMN2) at exon 7 in people with Welander distal myopathy is associated with a decrease in TIA1 in skeletal muscle and increased TIA1 staining linked to SGs." (PMID 41561436, 2025). "Welander’s distal myopathy (OMIM# 604454) due to autosomal dominant or recessive mutation in the Tia1 cytotoxic granule-associated RNA binding protein (TIA1) gene causes weakness in the distal long extensors of the hand and feet." (PMID 36399165, 2023). "TIA1 p.E384K mutation is the genetic cause of Welander distal myopathy (WDM), a late-onset muscular dystrophy whose pathogenesis has been related to modifying SG dynamics." (PMID 35269506, 2022). "Welander distal myopathy results from a missense change in the prion-like domain of TIA1, whereas a variant affecting a nearby amino acid residue leads to an identical distal myopathy phenotype in combination with SQSTM1 mutations." (PMID 33974137, 2021). "Missense mutations in the TIA1 gene cause both Welander distal myopathy (WDM) and ALS, characterized by delayed SG disassembly and accumulation of non-dynamic SGs that harbor TDP43." (PMID 32582692, 2020). "For example, mutations in hnRNPA1 and hnRNPA2/B1 were found in ALS families and in multisystem proteinopathy, TIA1 mutations were identified in Welander distal myopathy and also associated with stress granule formation in ALS." (PMID 25299611, 2014). "The missense E384K TIA1 autosomal dominant mutation is known to cause Welander distal myopathy." (PMID 41786146, 2026). "On the other hand, TIA1 expression, function, or regulation disorders are associated with different illnesses, among which are neurological diseases, viral infections, post-traumatic stress, cancer, and muscular diseases like Welander distal myopathy (WDM)." (PMID 39682710, 2024). "The p.E384K mutation of TIA1 is the genetic cause of Welander distal myopathy (WDM)." (PMID 35269506, 2022). "Mutations in TIA1 were recently linked to Welander distal myopathy; this fact combined with the role of TIA1 as a core stress granule gene lead us to hypothesize that we might also find mutations in TIA1 in sALS cases." (PMID 25299611, 2014). "Dominant mutations in the PrLD of the RBP T-cell-restricted intracellular antigen-1 (TIA1) cause several phenotypes including ALS, FTD and a rimmed vacuolar myopathy, called Welander distal myopathy (WDM)." (PMID 39501809, 2024). "Welander distal myopathy (WDM) is a late-onset muscular dystrophy that has been linked to a single-nucleotide substitution (c.1362G>A; p.E384K) in the gene encoding the TIA1 protein, which impacts TIA1-dependent SGs dynamics." (PMID 39682710, 2024). "No significant genotype–phenotype correlation has been identified in MSP and MSP‐like disorders with the exception of TIA1 c.1150G > A (p.Glu384Lys) resulting in isolated Welander distal myopathy, as observed also in our cohort." (PMID 36861178, 2023). "Mutations in the PrLD of TIA1 can cause the formation of insoluble (pathological) aggregates and are associated with several neurodegenerative diseases, including FTD and ALS, and Welander distal myopathy (WDM)." (PMID 41188647, 2025). "However, dysfunction of SGs due to TIA1 mutations has also been linked to muscle diseases, most notably Welander distal myopathy (WDM)." (PMID 35269506, 2022). "Previous studies in the literature have reported the involvement of TIA1 in neuropathologies including ALS, tauopathies, spinal muscular atrophy (SMA), stress-related psychiatric disorders, Huntington’s disease (HD), Welander distal myopathy (WDM), tumorigenesis, diabetes and lipid metabolism." (PMID 38534464, 2024).
colorectal cancer (15 papers, 2010 to 2025). A primary or metastatic malignant neoplasm that affects the colon or rectum. "Along these lines, TIA1 has been proposed as a prognostic marker in lung squamous cell carcinoma, colorectal cancer and urothelial cancer, wherein higher TIA1 expression is associated with better prognosis." (PMID 35163320, 2022). "Consistent with this role of TIA1, increased infiltration of TIA1+ lymphocytes is associated with improved prognosis of patients diagnosed with colorectal cancer." (PMID 32932781, 2020). "The prognostic effect of CD8+ TILs is confounded by the presence of TIA-1+ which translates into improved risk stratification for approximately 35% of all patients with MMR-proficient colorectal cancers." (PMID 21179245, 2010). "MiR-19a also promotes cell proliferation and migration by targeting the tumor suppressor T-cell intracellular antigen 1 (TIA1) in colorectal cancer and is upregulated in bladder cancer, where it correlates with aggressive tumor phenotypes." (PMID 40004152, 2025). "RNA binding protein TIA1 can be targeted by mir-19a, thus affecting cell proliferation and migration in colorectal cancer cells." (PMID 35962324, 2022). "For instance, in colorectal cancer, miR‐19a targets TIA1, an important tumor suppressor, leading to cell proliferation and increased migration." (PMID 35417090, 2022). "Immunoprecipitation of TIA1 followed by transcriptome-wide analyses of co-eluted RNAs have been carried out on colorectal carcinoma (RKO) and HEK293 cells for unbiased identification of TIA1 target RNAs in non-stressed conditions." (PMID 34410578, 2021). "miR-19a-3p also reported to be involved in the proliferation of colorectal cancer by targeting TIA1 and regulates progression of glioma by targeting RUNX3 directly." (PMID 33014522, 2020). "TIA1, whose binding motif matched with KER_842, has an isoform expression that is measured in colorectal cancers." (PMID 31703384, 2019). "For example, miR-19a contributed to colorectal cancer proliferation and migration by targetting TIA1." (PMID 30042169, 2018). "Only a handful of studies have evaluated TIA-1 expression on TILs in colorectal cancer, relating up-regulation to apoptosis and an increased number of TIA-1+ TILs in MMR-deficient tumors." (PMID 21179245, 2010). "To summarize, TIA-1 is a robust prognostic immunological biomarker that contributes to clinical outcome in patients with MMR-proficient colorectal cancers independently of TNM stage and adjuvant therapy." (PMID 21179245, 2010). "The novel findings of this study on 1406 MMR-proficient colorectal cancer patients suggest first, that higher numbers of TIA-1+ TILs represent a favourable and independent prognostic parameter and second that in addition to CD8, TIA-1 improves the prognostic stratification of patients by 35%." (PMID 21179245, 2010). "Although the prognostic significance of abundant CD8+ TILs has previously been established, this study goes one step further to identify the marker TIA-1 as a highly relevant prognostic parameter in colorectal cancer and particularly in tumors with marked cytotoxic CD8+ TILs." (PMID 21179245, 2010). "Of note, one VCP patient developed colorectal cancer during the time of follow‐up (at age 66) and 3 other patients (1 VCP, 2 SQSTM1 + TIA1) had prostate cancer." (PMID 36861178, 2023). "TIA-1 adds prognostic information to TNM stage and adjuvant therapy in MMR-proficient colorectal cancer patients." (PMID 21179245, 2010). "We next analyzed the phenotypic frequencies of the 1019 colorectal cancers with both evaluable CD8 and TIA-1 staining." (PMID 21179245, 2010). "Moreover, TIA1 can be used to supplement prognostic information related to TNM stage and adjuvant therapy in mismatch repair-proficient colorectal cancer patients." (PMID 28257633, 2017).
colorectal cancer (continued). "In this group of MMR-proficient colorectal cancer, only 7 patients had tumors with CD8+/TIA-1- TILs In univariable analysis, survival time differences for patients with CD8+/TIA-1+ TILs were significantly higher compared to patients with absence of CD8+ TILs (p<0.0001)." (PMID 21179245, 2010). "Indeed, in colorectal cancer, TIA1 downregulation contributes to the induction of pro-inflammatory mediators (e.g., COX-2), thus promoting cancer growth, while in esophageal squamous cell carcinoma, TIA1 acts as an oncogene by protecting the mRNAs from other oncogenes (e.g., SKP2, CCNA2)." (PMID 35406476, 2022). "In colorectal cancer (CRC), we found that TIA1 protein, but not its mRNA, was downregulated." (PMID 28257633, 2017).